PLA2R1 (phospholipase A2 receptor 1)
Diseases named in the same sentence as PLA2R1 in open-access papers (continued):
Sharing a sentence is not in itself a finding about the gene and the disease.
thyroid tumor (3 papers, 2020 to 2023). A benign or malignant neoplasm affecting the thyroid gland. "Data from a larger population and multiple centers are needed to evaluate the expression and application of PLA2R1 in thyroid tumors." (PMID 37345058, 2023). "It suggests that the overexpression of PLA2R1 could inhibit EMT in thyroid tumor." (PMID 37345058, 2023). "Furthermore, the in vivo tumorigenic assays revealed that the overexpression of PLA2R1 could inhibit the growth and proliferation of the thyroid tumor by modulating the ITGB1/FAK-signaling axis, compared to the control group in the animal study." (PMID 37345058, 2023). "SLC25A15, DIRAS2, PLA2R1, and MTARC1 expression was downregulated in thyroid tumorous tissues with LNM compared thyroid tumorous tissues with NLNM, which was validated using the TCGA dataset." (PMID 36106120, 2022).
acute lymphoid leukaemia (2 papers, 2018 to 2020). "The present study establishes that in addition to adult patients with AML19, the PLA2R1 promoter is also hypermethylated, both in BM aspirates and PB samples from paediatric patients with primary and relapsed acute lymphoblastic leukaemia." (PMID 32493972, 2020).
acute myeloid leukaemia (2 papers, 2012 to 2020). "According to the PLA2R1 bisulfite sequencing analysis, 77 CpG sites at −473 bp to +586 bp from exon 1 were found to be hypermethylated in blood leukocytes of adult patients with acute myeloid leukaemia compared to healthy individuals." (PMID 32493972, 2020). "Furthermore, measurements of PLA2R1 methylation appeared useful for predicting responsiveness to the methyltransferase inhibitor, azacitidine, as a pre-emptive treatment to avoid hematological relapse in patients with high-risk MDS or acute myeloid leukemia." (PMID 23217014, 2012).
coronary artery disease (2 papers, 2014 to 2025). "The PLA2R1 gene has been proposed as a candidate for coronary artery disease in subjects with normal levels of total cholesterol and very recently the Pla2r-deficient mice were shown to be susceptible to cardiac rupture after myocardial infarction." (PMID 25296178, 2014).
inflammatory bowel disease (2 papers, 2020). A spectrum of small and large bowel inflammatory diseases of unknown etiology. "Another observation is that all four genome-wide significant risk loci (PLA2R1, IRF4, NFKB1, and HLA) exhibit highly pleiotropic effects and all four lead SNPs have a concordant effect on the risk of inflammatory bowel disease (IBD)." (PMID 32231244, 2020).
liver steatosis (2 papers, 2023 to 2024). "In our study, the loss of Pla2r1 was associated with decreased levels of senescence marks and a better ability to regulate glucose metabolism, as well as a reduction in liver steatosis and fibrosis, which is consistent with the fact that senescent cell accumulation can promote these alterations." (PMID 37667516, 2023). "Therefore, the loss of Pla2r1 might decrease lipid accumulation mainly through a decrease in the liver of the synthesis and uptake of lipids to hepatocytic droplets, leading to less severe hepatic steatosis." (PMID 37667516, 2023). "Therefore, it seems that the loss of Pla2r1 could decrease lipid accumulation mainly through a decrease in TG hydrolysis and hepatic uptake of fatty acids, and also maybe by reducing hepatic de novo lipogenesis, consequently leading to less severe hepatic steatosis." (PMID 37667516, 2023). "Indeed, we demonstrated that Pla2r1 was directly involved in decreasing the ability of aged/WD‐fed mice to regulate their glucose and fat metabolism, leading to disorders such as hepatic steatosis, fibrosis, and cirrhosis." (PMID 37667516, 2023).
myelodysplastic syndrome (2 papers, 2012 to 2020). A clonal hematopoietic disorder characterized by dysplasia and ineffective hematopoiesis in one or more of the hematopoietic cell lines. "This study examined the expression and methylation of the PLA2R1 gene in Jurkat and U937 leukemic cell lines and its methylation in patients with myelodysplastic syndrome (MDS) or acute leukemia." (PMID 23217014, 2012). "Additionally, the PLA2R1 methylation degree was found to increase with disease stage progression in a group of myelodysplastic syndrome (MDS) patients." (PMID 32493972, 2020).
myocardial infarction (2 papers, 2014 to 2023). Gross necrosis of the myocardium, as a result of interruption of the blood supply to the area, as in coronary thrombosis. "For instance, Pla2r1 promoted collagen deposition in the liver during a Western diet in our study and was shown to do so in mouse lungs when Pla2r1 is overexpressed or in the heart after myocardial infarction." (PMID 37667516, 2023).
Obesity (2 papers, 2024 to 2025). Accumulation of substantial excess body fat. "The univariate analysis revealed that BMI, ALT > 40 U/L, TG > 1.7 mmol/L, IR, and PLA2R1 rs35771982 were significantly associated with an increased risk of moderate-severe MASLD in patients without obesity." (PMID 38836837, 2024). "Patients without obesity with MASLD had the highest proportion of the PLA2R1 rs35771982 Guanine, G (GG) genotype, followed by patients with obesity with MASLD and healthy controls (61.5% vs. 45.5% vs. 49.0%, p = 0.028)." (PMID 38836837, 2024). "This study found, that PLA2R1 rs35771982 and rs3749117 were associated with susceptibility to MASLD with and without obesity, as well as progression to steatohepatitis." (PMID 38836837, 2024).
renal carcinoma (2 papers, 2014 to 2024). A carcinoma arising from the epithelium of the renal parenchyma or the renal pelvis. "Knockdown of PLA2R1 increases renal cancer cell tumorigenicity supporting a role of PLA2R1 loss to promote in vivo RCC growth." (PMID 24657971, 2014).
renal cell carcinoma (2 papers, 2014 to 2018). "The inhibitory role of PLA2R1 in LNCaP xenografted cells is in agreement with the data observed by others with human renal cell carcinoma in in vivo mouse model." (PMID 30542512, 2018). "Here we report that PLA2R1 expression strongly decreases in samples of human renal cell carcinoma (RCC)." (PMID 24657971, 2014).
skin cancer (2 papers, 2015 to 2025). "The importance of PLA2R1 for regulation of cell life span was confirmed in vivo, as PLA2R1 knockout mice were more sensitive to RAS-induced skin tumours." (PMID 26672991, 2015).
thyroid cancer (2 papers, 2023). "In contrast, little is known about the underlying mechanism by which PLA2R1 regulates tumor progression in thyroid cancer." (PMID 37345058, 2023). "We found that the phospholipase A2 receptor 1 (PLA2R1) was expressed at low levels in thyroid cancer and that low PLA2R1 expression was associated with poor prognosis." (PMID 37345058, 2023). "Next, we conducted coimmunoprecipitation (Co-IP) experiments and western blotting to explore the underlying mechanism of PLA2R1 in regulating the growth of thyroid cancer." (PMID 37345058, 2023). "We aimed to uncover the underlying mechanism of PLA2R1 in thyroid cancer." (PMID 37345058, 2023). "Immunohistochemical staining was used to evaluate PLA2R1 expression in differentiated thyroid cancer (DTC) tissues." (PMID 37345058, 2023). "8505c cells had a lower PLA2R1 expression, and FTC133 cells had a higher PLA2R1 expression than the other thyroid cancer cell lines." (PMID 37345058, 2023). "In the following study, it was found that the overexpression of PLA2R1 inhibited the proliferation and invasion of thyroid cancer cells, while the knockdown of PLA2R1 had the opposite effects." (PMID 37345058, 2023). "We investigated the mechanism of PLA2R1 in thyroid cancer and provided a new strategy for thyroid cancer treatment that targets PLA2R1." (PMID 37345058, 2023). "We found that PLA2R1 was expressed at low levels in thyroid cancer tissues and that its expression level was positively correlated with prognosis." (PMID 37345058, 2023). "The overexpression of PLA2R1 significantly suppressed thyroid cancer cell proliferation and migration, and both of these effects were partially attenuated by the knockdown of PLA2R1." (PMID 37345058, 2023). "In this study, we evaluated the PLA2R1 expression in thyroid cancer tissues of different T grades through bioinformatics analysis and clinical sample analysis." (PMID 37345058, 2023). "In short, PLA2R1 knockdown promotes the tumorigenesis and proliferation of thyroid cancer via the FN1-mediated ITGB1/FAK axis in vivo." (PMID 37345058, 2023). "PLA2R1 is a promising biological candidate for exploitation in thyroid cancer." (PMID 37345058, 2023). "We speculate that PLA2R1 might be a promising marker and a novel therapeutic target for thyroid cancer." (PMID 37345058, 2023). "PLA2R1 competed with FN1 to bind ITGB1 to mediate extracellular matrix remodeling and thereby inhibit thyroid cancer progression." (PMID 37345058, 2023). "By attenuating the interaction of FN1 with ITGB1, overexpressed PLA2R1 suppresses the activation of the downstream FAK-signaling pathway, which in turn influences the malignant proliferation of thyroid cancer cells." (PMID 37345058, 2023). "The thyroid cancer cell lines 8505c and FTC133 transfected with PLA2R1 overexpression or knockdown plasmids were used for CCK8 assays and a wound healing assay." (PMID 37345058, 2023). "In addition, according to the results of Co-IP, FN1 expression was negatively correlated with PLA2R1 expression and positively correlated with ITGB1 expression in thyroid cancer." (PMID 37345058, 2023). "However, the role and mechanism of PLA2R1 in thyroid cancer has not been elucidated." (PMID 37345058, 2023). "However, the mechanism of action of PLA2R1 in thyroid cancer has not been fully elucidated." (PMID 37345058, 2023). "Therefore, we hypothesized that the overexpressed PLA2R1 competes with FN1 to bind ITGB1 and inhibit the activation of the downstream FAK-signaling pathway by attenuating the interaction between FN1 and ITGB1, thereby affecting the malignant proliferation of thyroid cancer cells." (PMID 37345058, 2023).
chordoma (1 paper, 2024). Chordomas are rare malignant tumors arising from embryonic remnants of the notochord in axial skeleton. "We have characterized the proteome of four chordoma cell lines and uncovered PLA2R1 as a novel cell-surface protein required for chordoma cell survival and association with patient outcome." (PMID 38454495, 2024). "Systematic data integration prioritized PLA2R1 (secretory phospholipase A2 receptor-PLA2R1) as a chordoma-enriched surface protein." (PMID 38454495, 2024). "Using siRNA- and CRISPR/Cas9-mediated knockdown of PLA2R1, we demonstrated significant inhibition of 2D, 3D and in vivo chordoma growth." (PMID 38454495, 2024). "The expression profile of PLA2R1 was validated across chordoma cell lines, patient surgical tissue samples, and normal tissue lysates via immunoblotting." (PMID 38454495, 2024). "PLA2R1 depletion resulted in cell cycle defects and metabolic rewiring via the MAPK signaling pathway, suggesting that PLA2R1 plays an essential role in chordoma biology." (PMID 38454495, 2024).
colon adenoma (1 paper, 2021). An adenoma that arises from the colon. "Two Pla2r1 KO mice displayed tumors, a lung adenoma, and a colon adenoma, suggesting an increased sensibility of Pla2r1 KO mice to develop tumors with aging." (PMID 33594040, 2021).
Fanconi anemia (1 paper, 2021). Fanconi anemia (FA) is a hereditary DNA repair disorder characterized by progressive pancytopenia with bone marrow failure, variable congenital malformations and predisposition to develop hematological or solid tumors. "Indeed, analysis of multiple human datasets using SEEK database support a strong anti-correlation between PLA2R1 levels and the Fanconi anemia pathway." (PMID 33594040, 2021).
Glucose intolerance (1 paper, 2023). Glucose intolerance (GI) can be defined as dysglycemia that comprises both prediabetes and diabetes. "Old Pla2r1‐deficient mice (21 months) and their WT controls were analyzed for several features of aging, such as immunosenescence, defined as aging of the immune system, systemic glucose intolerance, and insulin resistance, telomere shortening and liver alterations." (PMID 37667516, 2023). "Strikingly, Pla2r1 KO mice responded in a similar manner to glucose challenge at the beginning (D0) and at the end of the WD (D77), highlighting protection against WD‐induced glucose intolerance." (PMID 37667516, 2023).
Liver fibrosis (1 paper, 2023). "Expression of Col1a1, a major component of collagen, and of Tgfb1 an important promoter of fibrosis was also stronger following administration of the WD in WT mice compared with Pla2r1 KO mice, further supporting that Pla2r1 KO mice were protected from liver fibrosis." (PMID 37667516, 2023).
mental disorder (1 paper, 2020). A disease that has its basis in the disruption of mental process. "These nucleotide substitutions were found in the messenger RNAs (mRNAs) of 14 genes, two of which (Pla2r1 and Yars) are known to be associated with mental disorders and neurodegenerative diseases, respectively." (PMID 32429546, 2020). "In addition, the Pla2r1 gene is known to be associated with mental disorders, and Ccdc28b is related to retinal dystrophy." (PMID 32429546, 2020). "In addition, Ephx1 and several other genes (Pla2r1, Zmym6, Trappc9, and Nqo2) are annotated in the RGD as genes associated with neurodegenerative diseases and/or mental disorders." (PMID 32429546, 2020).
myocardial ischemia (1 paper, 2020). A disorder of cardiac function caused by insufficient blood flow to the muscle tissue of the heart. "However, sPLA2-IIA might not be the only one in the family, since recent evidence in a model of myocardial ischemia has pointed out that other isoforms, sPLA2-IB and sPLA2-IIE and its receptor PLA2R1, might mediate collagen-dependent biological effects in the infarcted myocardium." (PMID 32046347, 2020).
obstructive lung disease (1 paper, 2025). "For instance, studies have demonstrated that PLA2R1 can mediate premature aging phenotypes and drive detrimental lung cell senescence in obstructive lung disease." (PMID 41497980, 2025).
cancer (46 papers, 2013 to 2026). A tumor composed of atypical neoplastic, often pleomorphic cells that invade other tissues. "Aberrant expression of PLA2R1 has been associated with the development and progression of different types of cancer." (PMID 32751713, 2020). "Among miRNAs, which were positively associated with PLA2R1 expression in this study, hsa-miR-23b and −154 exerted suppressing effects in different cancers in vitro and in vivo." (PMID 26672991, 2015). "Surprisingly, 41% of patients with cancer-associated MN had anti-PLA2R1 antibodies." (PMID 33828546, 2021). "In PLA2R1-ab positive patients, antigen-specific IgG1, IgG2, and IgG3 antibodies were positive in 72 vs. 88%, 28 vs. 25%, and 100 vs. 94% of patients with primary vs. malignancy-associated MN, respectively." (PMID 30619370, 2018). "In addition to the 16 PLA2R1-ab positive patients with malignancy, we included further 60 patients from our prospective cohort of patients with PLA2R1-associated MN in this study." (PMID 30619370, 2018). "Nevertheless, it has been shown to be activated during cancer cell death in response to PLA2R1/JAK/STAT signalling, this signalling being known to promote cellular senescence in normal human cells and in mice." (PMID 38216569, 2024). "Studies have demonstrated that PLA2R1 is involved in several important biological processes in cancer, including triggering DNA damage, carcinogenesis, cell death and cell differentiation." (PMID 37345058, 2023). "It has been previously documented that PLA2R1 can inhibit cancer progression by activating the Janus kinase 2 (JAK2) pathway and inducing estrogen-related receptor alpha (ESRRA)." (PMID 37345058, 2023). "Despite the strong evidence supporting the role of PLA2R1 in cancer suppression, the mechanism of this role still needs to be further explored." (PMID 37345058, 2023). "Functional experiments have demonstrated that PLA2R1 controls cancer cell death by influencing mitochondrial biology." (PMID 36106120, 2022). "PLA2R1 is down-regulated in a number of cancer types, which supports its tumor suppressor role, and its expression can be suppressed by c-MYC and HIF2α, the oncogenes." (PMID 34112138, 2021). "Previous in vitro studies explained the mechanism of the PLA2R1 promoter hypermethylation in various types of cancer." (PMID 32751713, 2020). "In cancer cells, PLA2R1 expression is generally decreased and its constitutive expression results in tumor growth inhibition while its reduction fosters cancer progression." (PMID 32424163, 2020). "Mechanistically, cancer cells endorse PLA2R1 promoter hypermethylation to diminish its tumor suppressive effects, enhancing tumorigenesis." (PMID 32751713, 2020). "These novel findings on the epigenetic control of PLA2R1 and its link to the aggressive subtypes of mammary gland carcinomas open the door to new areas of research in cancer biology." (PMID 32751713, 2020). "The effect of PLA2R1 expression on cancer formation and progression remains controversial as PLA2R1 was shown to have both tumour-suppressive and pro-oncogenic properties dependent on the investigated cell type." (PMID 30542512, 2018). "We suggest that, after systematic screening for classical secondary cause of MN, the analysis of PLA2R1 and THDS7A (especially in MN associated with cancer) is indicated." (PMID 29511687, 2018). "Circulating anti-phospholipase A2 receptor 1 (anti-PLA2R1) antibodies are frequently seen in idiopathic MN, while they are rarely found in cancer-associated MN." (PMID 26498294, 2016). "While the receptor is down-regulated in these cancers, significant up-regulation of PLA2R1 was described in the prostate cancer cell lines PC-3 and DU-145 in comparison to normal prostate cells." (PMID 26672991, 2015). "In normal cells and CAL-51 and UACC-812 cancer cell lines the PLA2R1 methylation degree was negligible (<10 %), whereas in MDA-MB-453 cells it reached a value of about 80 %." (PMID 26672991, 2015).